CDH11 (cadherin 11)
Diseases named in the same sentence as CDH11 in open-access papers (continued):
Sharing a sentence is not in itself a finding about the gene and the disease.
tumor (continued). "In this study, we demonstrate that CDH11 is involved in BC progression and that its inhibition has a tumor‐suppressive effect, suggesting that CDH11 is a potential therapeutic target molecule." (PMID 41263259, 2025). "While CDH11 KD did not alter cell proliferation, invasion, or migration in vitro, CDH11 KD significantly suppressed tumor growth in an in vivo subcutaneous xenograft mouse model." (PMID 41263259, 2025). "In contrast, our findings and reports from other cancer cell lines, reveal that suppression of CDH11 reduces tumor growth and metastasis in mouse models." (PMID 41263259, 2025). "CDH11 is a classical cell adhesion glycoprotein that mediates cell–cell adhesion and acts as a tumor suppressor in RB." (PMID 38920989, 2024). "Primary ABC has been proposed to be a true neoplasm as it contains rearrangements of CDH11 and USP6 genes." (PMID 39462411, 2024). "During epithelial–mesenchymal transition (EMT) in cancer progression, tumor cells switch cadherin profile from E‐cadherin to cadherin‐11 (CDH11), which is accompanied by increased invasiveness and metastatic activity." (PMID 37558205, 2023). "Deep immunophenotyping showed that anti-CDH11 antibodies decreased the frequency of FOXP3+ T cells in the tumor." (PMID 36598557, 2023). "We also observed an increase in T cell infiltration and a loss of TAMs/MDSCs and neutrophils in the tumor of KPC-Cdh11+/- mice and identified several genes differentially expressed in these populations as a result of Cdh11-deficency." (PMID 37954069, 2023). "In this study, we examined both transcriptional and protein levels of CDH11 in multiple tumor types and reported that a high percentage of CDH11+ cells reside in a wide spectrum of tumors including brain, adrenal gland, skin, testis, ovary and breast." (PMID 37558205, 2023). "Surprisingly, while CDH11 is a junctional protein, it was found to localize in the nuclei of tumor cells from multiple tumors including breast, lymph node, ovary, lung and palate." (PMID 37558205, 2023). "Further studies utilizing conditional knockouts and Cdh11 inhibition post-tumor formation will be required to confirm the role of CAF-derived Cdh11 in altering the tumor immune microenvironment." (PMID 37954069, 2023). "Understanding how Cdh11 promotes an immunosuppressive tumor microenvironment in PDAC will provide invaluable insights into developing new clinical approaches for effective eradication of cancer cells, in solid tumors that are classically immunodeficient." (PMID 37954069, 2023). "In other cancers, such as gastric cancer and retinoblastoma, the CDH11 gene is hypermethylated and silenced, functioning as a tumor suppressor." (PMID 37013637, 2023). "ECM-related integrin, beta-like 1 (ITGBL1), cadherin 11 (CDH11) and trophinin-associated protein (TROAP) were upregulated, perhaps reflecting a reorganisation of the tumour microenvironment that is permissive of invasion and metastasis." (PMID 38124114, 2023). "H‐score was then computed based on the intensity of CDH11 staining in each tumor sample (see Section 2 for details)." (PMID 37558205, 2023). "It was noted that the expression of CDH11, COL6A3, EDNRA, and SERPINF1 were negatively associated with tumor purity." (PMID 36595851, 2022). "Crossing of Cdh11 null mice with TAg-RB, RB model mice, resulted in faster tumor growth than Tag-RB alone through downregulation of tumor cell death, proposing that CDH11 works as a tumor suppressor through activation of cell–cell interaction." (PMID 36230849, 2022). "From the TIMER web resource, the association between CDH11, COL6A3, EDNRA, and SERPINF1 immune signatures and tumor purity or numerous vital immune cells was revealed." (PMID 36595851, 2022). "CDH11 inhibits cell invasion and proliferation, induces tumor cell apoptosis, and finally achieves its anti-cancer effect through Wnt/β-catenin and AKT/Rho A signaling pathways." (PMID 33442417, 2021).
tumor (continued). "On the other hand, Cadherin-11 promotes adhesion between osteoclast precursors and increases the production of specific collagens, which facilitates fibrotic changes in the tumor microenvironment." (PMID 33478523, 2021). "In human cancer, CDH11 promotes tumor development via controlling NF‐κB, EMT, and Wnt/beta‐catenin pathways." (PMID 32463580, 2020). "CDH11 is considered an adhesion factor involved in calcium-dependent cell–cell adhesion, and elevated CDH11 expression in tumor cells can suppress tumor formation by inducing tumor cell apoptosis, suppressing EMT, and reducing stemness." (PMID 30828336, 2019). "Taken together, these findings suggest that CDH11 play an important role in tumorigenicity and tumor growth of TNBC cells in vivo." (PMID 30691241, 2019). "After establishing the role of CDH11 role as an actionable inductor and/or modulator of metastasis and stemness in vitro, we utilized the murine tumor xenograft model for in vivo validative studies." (PMID 31248373, 2019). "Using murine tumor xenograft models, we demonstrated in vivo that anti-CDH11 antibody treatment significantly reduces distant metastasis in MCF7 or MDA-MB-231-bearing mice." (PMID 31248373, 2019). "After inoculation with MDA-MB-231 or MCF cells, the tumor-bearing mice were randomly divided into control and anti-CDH11 groups." (PMID 31248373, 2019). "CDH11 was identified to participate in multiple BPs including bone formation, cellular signal transduction, tumor invasion, and metastasis, and also play important roles in developmental and pathogenic mechanisms of heart valve." (PMID 31921308, 2019). "Global profiling of matched cell lines from metastasis and primary tumour identified CDH11 as a target of silencing via DNA methylation and subsequent functional analysis supported a role for CDH11 in metastasis suppression." (PMID 27756687, 2017). "Searching for predicted and validated miR-335 target genes, we found that PLAUR (p = 0.046) and CDH11 (p = 0.049) are potential targets which participate in metastasis and tumor invasion pathway." (PMID 29075357, 2017). "Cadherins CDH19, CDH16, CDH11 were found to be down regulated in OTSCC tumor as a read out of EMT process." (PMID 27280700, 2016). "CDH11 is expressed by multiple tumor cells of epithelial origin and correlated with poor differentiation and cancer aggressiveness." (PMID 26090476, 2015). "We go on to show that CDH11 is necessary for MDA-MB-231 cell tumor growth and that it regulates proliferation, colony formation, migration and invasion of several CDH11 positive tumor cells." (PMID 24681547, 2014). "We further show that CDH11 can be directly targeted in tumor cells using CDH11 antibodies and repositioned drugs such as celecoxib that are effective in RA." (PMID 24681547, 2014). "Increased expression of the mesenchymal cadherins N-cadherin and/or cadherin-11 (CDH11) and decreased E-cadherin, have been associated with both EMT and tumor progression." (PMID 24681547, 2014). "Although CDH11 is elevated in cancer stromal tissue, stromal tissue likely contains tumor cells in the process of invasion as well as host stromal cells and it is not clear which population contributes to the observed increases in mRNA." (PMID 24681547, 2014). "It has been suggested that tumor-promoting inflammation and antitumor immunity coexist at different points along the path of tumor progression, and a recent report has demonstrated that CDH11 was a key mediator of fibroblast inflammation." (PMID 23971040, 2013). "In many areas, intense Cdh11 immunoreactivity was observed in tumor cells in adjacent to tumor vessels." (PMID 23951053, 2013). "As CDH11 upregulation is likely only one of multiple mesenchymal characteristics, it would appear unlikely that CDH11 or any individual molecule will prove to be the sole determinant of tumor aggressiveness." (PMID 23951053, 2013).
tumor (continued). "Our findings expand on previous studies to propose that endothelial cells not only support the self-renewal of tumor stem cells, they also stimulate cell motility via CDH11." (PMID 23951053, 2013). "Most importantly, the study of CDH11 5′-CpG island hypermethylation in primary tumours and lymph node metastases of cancer patients showed this epigenetic alteration to be significantly confined to the disseminated cells." (PMID 22374749, 2012). "In sharp contrast, we observed that the stable down-regulation of CDH11 by the short hairpin RNA (shRNA) approach in CDH11-expressing and unmethylated primary tumour-derived cells (SIHN011A) had the opposite effects." (PMID 22374749, 2012). "This protein has been studied in relation to its influence on cancer cell behaviour, mainly regarding its metastatic capacity, and a wide range of roles has been assigned to CDH11, varying with the tumour types examined." (PMID 22374749, 2012). "Using in vitro and in vivo cellular and mouse models for depleted or enhanced CDH11 activity, we also demonstrated that CDH11 acts as an inhibitor of tumour growth, motility and dissemination." (PMID 22374749, 2012). "Tumours originating from CDH11 shRNA-down-regulated SIHN011A cells had significantly greater weights and volumes than those derived from scrambled shRNA cells." (PMID 22374749, 2012). "Most importantly, we also show in vitro and in vivo that CDH11 functions as a metastasis-tumour suppressor gene." (PMID 22374749, 2012). "Our data suggest that hypermethylation-induced silencing of CDH11 is a facilitating event for the scattering of tumour cells, by loosening cell–cell contacts and intravasation into blood or lymphatic vessels." (PMID 22374749, 2012). "Previous studies in epithelial tumor cells have shown that mesenchymal cadherins (i.e. N-cadherin and cadherin 11) can promote tumor cell growth and migration via p120-mediated activation of Rac1 signaling." (PMID 21060868, 2010). "Tumor volumes as a percent of retina were estimated to be 5.0%, 3.2% and 1.5% in Cdh11+/+;TAg+/-, Cdh11+/-;TAg+/- and Cdh11-/-;TAg+/- genotypes respectively (5 animals analyzed per genotype)." (PMID 20421947, 2010). "This tumor cell line, when treated with cadherin-11 siRNA, showed significant cadherin-11 knockdown." (PMID 20421947, 2010). "Once in the bone, it is possible that these cadherin-11-expressing tumor cells activate either osteoclasts or osteoblasts, depending on the type of cancer metastasis, leading to bone remodeling." (PMID 19274078, 2009). "Thus, further investigation is required to determine its efficacy in inhibiting CDH11 for tumor treatment." (PMID 39739317, 2025). "CDH11 is important for tumor growth in vivo, and administration of CDH11 inhibitors suppressed tumor growth in the xenograft mouse model without weight loss or death." (PMID 41263259, 2025). "IFN‐β released after CXB, DMC, or SD133treatment plays a crucial role in stimulating tumor‐specific T cell response and may act as a mediator between the CDH11 inhibitor and immune response activation." (PMID 39739317, 2025). "Furthermore, use of a CDH11 inhibitor resulted in decreased mitochondrial activity in vitro, and CDH11 inhibitor resulted in inhibition of tumor growth in vivo." (PMID 41263259, 2025). "Consequently, targeting CDH11 holds a great promise for drug therapy, as it can significantly suppress the tumor lung metastasis." (PMID 39739317, 2025). "We evaluated tumor growth and mitochondrial energy metabolism using a CDH11 inhibitor (Sd‐133)." (PMID 41263259, 2025). "In addition to its role as an effector molecule, CDH11 exerts regulatory effects on tumor cell function through alternative signaling pathways." (PMID 39739317, 2025). "However, the mechanisms by which Cdh11 deficiency influences PDAC progression and anti-tumor immune responses have yet to be fully elucidated." (PMID 37954069, 2023).
tumor (continued). "Downregulation of Cdh11 (Cadherin-11) might also result in reduced tumor cell adhesion as Cadherin-11 was identified as regulator of cell adhesion and metastasis in many cancers." (PMID 37179302, 2023). "Our findings may also be extended to other tumor cells with high CDH11 expression, but further studies are needed to verify this hypothesis." (PMID 37558205, 2023). "Next, we used the online platform GEPIA (Gene Expression Profiling Interactive Analysis) to analyze The Cancer Genome Atlas (TCGA) RNA‐seq data, in terms of the transcription levels of CDH11 across all tumor samples and compared them with paired normal tissues." (PMID 37558205, 2023). "Moreover, the percentage of CDH11+ cells in the tumor areas was significantly higher when compared with the surrounding stroma (tumor: 66.6% vs. stroma: 48.2%, n = 219, P < 0.001)." (PMID 37558205, 2023). "In addition, classical EMT protein families that modulate cell communication processes, e.g. cadherins (CDH11), collagens, and focal adhesion components (integrins) were highly differentially expressed in the tumor samples." (PMID 38104152, 2023). "Moreover, because of the role of CDH11 as an inducer of metastatic signaling, targeting CDH11 triggered re-expression of the miR-335 tumor suppressor, which limited the CDH11-induced EMT." (PMID 36315446, 2022). "In addition, the ACTA2, ASPN, PDGFRB, PDPN, COL12A1, EMILIN1, and CDH11 genes were upregulated in CAFs of several tumor types." (PMID 36263012, 2022). "Therefore, CDH11 is a tumor promoter, which participates in the cytoskeleton reorganization and cell movement induced by MC-LR, so as to enhance the motility and invasiveness of cancer cells." (PMID 33442417, 2021). "Importantly, the number of tumor nodules derived MKN45P-PR/Flag-CDH11 cells were substantially reduced after intraperitoneal injection with PTX." (PMID 33391403, 2021). "DNA of tumor cell lines copy number distortion and 1-Mb hemizygote deletion at 16q21-22.1, and CDH11 is the sole known gene situated in the deletion, so CDH11 may be a candidate tumor suppressor gene related to 16q21-22.1 deletion." (PMID 33442417, 2021). "Croset et almiR-30 could inhabit tumor cell invasion by silencing CDH11 or ITGA5 in ER-/PR-negative breast cancer." (PMID 34252359, 2021). "On the other hand, Cadherin-11 mediated the adhesion between osteoclast precursors and upregulated the production of specific collagens, especially Collagen 5, which facilitated fibrotic changes in the tumor microenvironment." (PMID 33478523, 2021). "The results between CDH11 and the clinical features of GC patients showed that CDH11 overexpression is distinctly associated with worse pathological features such as EMT, metastatic status, higher T stage, and tumor mutation burden (TMB)." (PMID 32685527, 2020). "Thus, we also accounted for the interference of tumor purity when analyzing the relationship between CDH11 and immune cell infiltrations in TME." (PMID 32685527, 2020). "However, in malignant tumors of the head and neck, CDH11 is a tumor suppressor controlling the proliferation and invasion of cancer cells." (PMID 32685527, 2020). "Finally, in agreement with reduced tumor cell migration upon CDH11 silencing in CAF-S1 fibroblasts, we found that these conditions had an impact on CDH1/E-cadherin protein levels in both MCF7 and T47D tumor cells." (PMID 32665033, 2020). "Also, we obtained evidence that CDH11 has a significant correlation with infiltrating immune cells in the tumor microenvironment (TME)." (PMID 32685527, 2020). "This may be the result of interaction between tumor cells with high expression of CDH11 and infiltrating immune cells in the TME." (PMID 32685527, 2020). "Based on tumor purity, we ascertained that most cytokines are secreted by TAMs and M2 macrophages, and marker sets have significant correlations with CDH11 in STAD, with examples including CCL-2, TGFB1, CXCL12, and MPP2 of TAMs and IL-10, IL1R1, CD163, and MRC1 of M2 phenotype (P < 0.0001)." (PMID 32685527, 2020).
tumor (continued). "Similarly, the change in expression of E-cadherin to N-cadherin or the up-regulation of cadherin-11 and P-cadherin also favor tumor progression and are an indicator of more migratory and more invasive tumor types." (PMID 33076339, 2020). "Through a comprehensive analysis of CDH11 expression profiles of GC in multiple databases, we found that CDH11 is highly expressed in tumor tissues, which indicates that CDH11 may promote oncogenesis in the stomach." (PMID 32685527, 2020). "Maintenance of CDH1/E-cadherin protein levels in tumor cells upon co-culture with CAF-S1 could explain the reduction of tumor cell migration we observed upon CDH11 silencing in CAF-S1." (PMID 32665033, 2020). "In addition, downregulation of CDH11 promotes proliferation and enhances invasion, and CDH11 has tumor suppressor function." (PMID 30755200, 2019). "Expression of CDH11 in metastatic bone tumors is higher than in primary tumor sites." (PMID 30691241, 2019). "Finally, substantiating findings from our in vitro assays, our in vivo studies highlight the putative potential of CDH11-targeting to suppress tumorigenesis, and inhibit tumor growth in TNBC xenograft models, while concurrently improving survival time." (PMID 30691241, 2019). "In our studies cell proliferation and tumor growth were inhibited upon CDH11 depletion in MDA-MB-231 cells suggesting that a portion of the “metastatic” potential may be a result of alterations in cell proliferation." (PMID 24681547, 2014). "Forced CDH11 expression in HOXC8-knockdown cells did little on the rate of tumor outgrowth." (PMID 24810778, 2014). "As occurred with the cell lines, detailed bisulphite genomic sequencing analyses in the primary tumours detected a few CDH11 hypermethylated clones, from which the metastatic cells might have arisen." (PMID 22374749, 2012). "Restoration of CDH11 expression in hypermethylated cells caused a change from a rounded shape to an elongated one, and it is known that these latter cells are less able to intravasate and withstand shear stresses in circulation 41, further supporting the metastasis tumour-suppressor role of CDH11." (PMID 22374749, 2012). "Several of the upregulated genes encoded adhesion receptors, secreted proteins and cytoskeletal components, including CDH11, POSTN and MYO5B, along with RUNX1, a master regulator of differentiation processes in different tissues implicated in cell transformation and tumor progression." (PMID 21611158, 2011). "Even after adjusting for retinal size, the tumor volume per initiating cell in mice with mutant Cdh11 alleles remained significantly greater (p = 0.01, data not shown)." (PMID 20421947, 2010). "To establish whether tumors developing in Cdh11 mutant animals grew faster, we studied the rate of tumor growth between PND8 and PND84." (PMID 20421947, 2010). "Significantly reduced numbers of cells stained for pro-apoptotic proteins in tumors of mice with absent Cdh11 alleles, indicating that promotion of cell death is an important part of the tumor suppressor action of Cdh11." (PMID 20421947, 2010). "By crossing this CDH11 functional knockout with the TAg-RB mice, we report an unexpected result: Cdh11 allelic loss results in fewer tumor initiating TAg positive cells at PND8, and consequently fewer multifocal tumors at PND28 compared to animals with normal Cdh11 alleles." (PMID 20421947, 2010). "At PND9, early initiating tumour cells showed complete overlap of TAg and cadherin-11 staining." (PMID 20421947, 2010). "Therefore, the activation of cGAS‐STING mediated by a CDH11 inhibitor offers specific advantages, as it selectively targets tumor tissue when administered systemically, eliciting an antitumor immune response within the tumor microenvironment, while minimizing the side effects on normal tissue." (PMID 39739317, 2025).